FAAH (fatty acid amide hydrolase)
Diseases named in the same sentence as FAAH in open-access papers (continued):
Sharing a sentence is not in itself a finding about the gene and the disease.
Arthritis (2 papers, 2015 to 2021). Inflammation of a joint. "Mice were injected daily with JNJ1661010, a potent and selective inhibitor of FAAH and treatment reduced arthritis score in comparison to control animals." (PMID 26567045, 2015). "AEA reduced several inflammatory mediators and therefore the influence of FAAH inhibition on experimental arthritis was investigated." (PMID 26567045, 2015).
Ataxia (2 papers, 2017 to 2018). Ataxia refers to impaired coordination of voluntary muscle movement. "Doses that maximally blocked FAAH activity (≥1 mg/kg, p.o.)produced no catalepsy, ataxia or hypomotility, three typical signs of CB1 receptor activation." (PMID 29403000, 2018). "This study demonstrates that certain elements of the endocannabinoid signaling system (CB1 receptors, the FAAH enzyme) are altered in the striatum of SCA-3 transgenic mice, as previously found in other important brain structures affected in this type of ataxia (cerebellum and brainstem)." (PMID 28448548, 2017).
atherosclerosis (2 papers, 2022). A disease characterized by the build-up of fatty material and calcium deposition in the arterial wall resulting in partial or complete occlusion of the arterial lumen. "Some mutated genes are related to atherosclerosis, such as FAAH, KALRN, ATP10D, CUBN, APOA5, and LRP1." (PMID 36071494, 2022). "In cardiovascular aging and atherosclerosis, FAAH knockout can decrease age-related cardiac dysfunction, myocardial nitrative stress, and inflammatory gene expression." (PMID 35602108, 2022).
autoimmune hepatitis (2 papers, 2020 to 2021). Hepatitis caused by autoantibodies. "In fact, studies using FAAH inhibitor or mice deficient in FAAH have shown that such approaches lead to an increase in AEA and consequent suppression of autoimmune hepatitis triggered by a polyclonal activator of T cells which triggers cytokine storm." (PMID 33240092, 2020). "In fact, in a previous study, we noted that FAAH knockout mice or administration of FAAH inhibitor could upregulate endogenous AEA leading to suppression of autoimmune hepatitis." (PMID 33995054, 2021).
Autoimmunity (2 papers, 2018 to 2023). The occurrence of an immune reaction against the organism's own cells or tissues. "In relation to autoimmunity, FAAH was also found to be upregulated in B-cells and led to a reduction in the number of polyreactive autoantibodies in lupus-prone mice." (PMID 37921652, 2023). "Our previous studies have implicated fatty acid amide hydrolase (FAAH) as a disease gene for autoimmunity, where heightened FAAH expression drives B-cell survival and B-cell driven autoimmunity." (PMID 37921652, 2023).
breast tumor (2 papers, 2013 to 2023). "To establish whether the association between higher FAAH mRNA levels and luminal tumor phenotypes also occurs at the protein level, we analyzed FAAH protein expression in a series of 617 human breast tumor samples included in several tissue microarrays (all here referred to as TMA #1)." (PMID 37253733, 2023). "Together, these findings strongly support that FAAH plays an important role in suppressing breast tumor progression and lung metastasis in mice." (PMID 37253733, 2023). "Thus, breast tumors generated by MMTV-neu:FAAH−/− mice expressed higher mRNA and protein levels of Cxcr4 and Cxcl12 than their FAAH-expressing counterparts, which is consistent with their enhanced aggressive behavior and metastatic rate." (PMID 37253733, 2023). "The cytoplasmic expression of FAAH was significantly up-regulated in invasive breast tumor tissues compared to the non-cancerous tissues." (PMID 23374458, 2013).
colon carcinoma (2 papers, 2020 to 2021). "Finally, we determined the effect of cannabis on the protein levels of FAAH and NAPE-PLD in Caco-2 cells (colon carcinoma epithelial cells)." (PMID 34531823, 2021). "Since both enzymes were expressed by the epithelial cells, we also exposed Caco-2 (colon carcinoma cells) to two chemovars of cannabis, with and without THC for 48 h, extracted their proteins, and evaluated the effect of cannabis exposure on FAAH and NAPE-PLD expression." (PMID 34531823, 2021).
Constipation (2 papers, 2019 to 2024). Infrequent or difficult evacuation of feces. "Similarly, inhibition of anti-diacylglycerol lipase (DAGL) and fatty acid amide hydrolase (FAAH)—two enzymes critical in endocannabinoid metabolism—has been shown to normalise transit time in the context of opioid-induced constipation." (PMID 37884682, 2024). "In line with our observation, the decreased expression of FAAH was found in the intestinal tissues of slow-transit constipation patients, suggesting that oleamide signaling might be implicated in the progress of FC." (PMID 32038247, 2019).
cystitis (2 papers, 2018 to 2021). Inflammation of the urinary bladder. "We observed decreased inflammation in bladders of FAAH-deficient (knock out or KO) mice with cyclophosphamide-induced cystitis." (PMID 29867382, 2018). "We also found that systemic treatment of rats with established cystitis with a FAAH inhibitor given 1 h prior to testing diminished referred mechanical hypersensitivity." (PMID 29867382, 2018). "Local inhibition of FAAH or MAGL within the bladder may be viable options to reduce pain associated with cystitis with fewer systemic side effects, but this has not been explored." (PMID 29867382, 2018). "Only two studies have reported the levels of FAAH and NAAA in experimental cystitis models, and FAAH and NAAA remained unaltered in both cases." (PMID 35054185, 2021).
endometriosis (2 papers, 2022 to 2025). The growth of functional endometrial tissue in anatomic sites outside the uterine body. "In particular, it was shown that FAAH and NAPE‐PLD transcripts did not significantly differ between endometrial stromal cells from endometriosis‐affected women and healthy controls whereas NAPE‐PLD, DAGL, FAAH and MAGL protein levels were reduced in endometriotic lesions." (PMID 41294926, 2025).
fragile X syndrome (2 papers, 2016 to 2022). A genetic syndrome caused by mutations in the FMR1 gene which is responsible for the expression of the fragile X mental retardation 1 protein. "As fatty acid amide hydrolase (FAAH) catalyzes the metabolism of the eCB anandamide, treatment with the FAAH inhibitor URB-597 improved performance in fragile X syndrome gene fmr1 KO mice, possibly via the anxiolytic effects of FAAH inhibition." (PMID 36077195, 2022).
gynecological cancers (2 papers, 2019 to 2024). "Whilst there have been no studies that have examined the activity of FAAH and NAPE-PLD in gynecological cancers, these have been studied in early pregnancy complications." (PMID 31921630, 2019).
lymph node metastasis (2 papers, 2013 to 2023). "A significant association between FAAH expression and patients with more than 4 axillary lymph node metastases (P = 0.023) was observed." (PMID 23374458, 2013). "In addition, the expression levels of FAAH were significantly increased in patients with higher number of axillary lymph node metastases." (PMID 23374458, 2013). "In addition, we have also demonstrated an association between elevated levels of FAAH and PIR and high number of axillary lymph node involvement and lymph node metastasis, respectively." (PMID 23374458, 2013). "However, elevated protein levels of FAAH were positively associated with high number of lymph node involvement and upregulated levels of PIR were positively related with lymph node metastasis." (PMID 23374458, 2013). "Analysis of clinicopathological parameters showed that the high expression of FAAH was related to the patient’s sex, tumour size, invasion depth, WHO classification and lymph node metastasis, but was not related to Lauren classification, degree of differentiation and H. pylori status of patients." (PMID 36702852, 2023).
lymphoma (2 papers, 2014). A malignant (clonal) proliferation of B- lymphocytes or T- lymphocytes which involves the lymph nodes, bone marrow and/or extranodal sites. "Like estrogen, progesterone can interact with a promoter region in the FAAH gene in that progesterone has been shown to increase FAAH expression in T-cells and human lymphoma U937 cells." (PMID 24550985, 2014). "MCL has high expression of a key enzyme in the anandamide synthesis, NAPEPLD and mostly low expression of the anandamide metabolizing enzyme FAAH, suggesting that high anandamide levels are favored in this lymphoma subtype." (PMID 25594062, 2014).
nicotine addiction (2 papers, 2011 to 2018). "In this regard, previous studies done with rodents have shown that fatty acid amide hydrolase (FAAH) may be involved in nicotine dependence." (PMID 30260990, 2018). "Together, these findings point to the possibility that FAAH inhibition may represent an effective pharmacological strategy for the treatment of nicotine addiction." (PMID 22140525, 2011).
non-alcoholic fatty liver disease (2 papers, 2012 to 2023). "As a fatty acid amide hydrolase inhibitor, BCA can slow down the progression of nonalcoholic fatty liver disease (NAFLD) by regulating cholesterol metabolism." (PMID 37111591, 2023).
pancreatic cancer (2 papers, 2010 to 2024). "In our study, hypomethylated and highly expressed FAAH correlated with a favorable prognosis, echoing findings in pancreatic cancer." (PMID 39575189, 2024).
postherpetic neuralgia (2 papers, 2021 to 2025). "A phase IIa trial assessed the analgesic effect and safety of ASP8477, a fatty acid amide hydrolase inhibitor, in 132 patients with painful diabetic peripheral neuropathy and postherpetic neuralgia." (PMID 33986899, 2021).
Pruritus (2 papers, 2019 to 2023). Pruritus is an itch or a sensation that makes a person want to scratch. "The anti-pruritic efficiency of FAAH-blockade was further shown in an allergenic model of pruritus." (PMID 30845666, 2019).
renal cell carcinoma (2 papers, 2023 to 2024). "The combination treatment with FAAH inhibitors, exemplified by URB597, and ferroptosis inducers has been shown to effectively inhibit the PI3K/Akt pathway in the context of renal cell carcinoma." (PMID 38562143, 2024). "For example, the PI3K-AKT pathway is downregulated by the combined treatment with URB597 (FAAH inhibitor) and RSL3 (ferroptosis inducer) in renal cell carcinoma (RCC) cells." (PMID 38562143, 2024).
Sensory neuropathy (2 papers, 2025). Peripheral neuropathy affecting the sensory nerves. "In a study by Nasirinezhad and team, FAAH inhibition significantly attenuated persistent pain-related behaviors in a rat model of human immunodeficiency virus (HIV) sensory neuropathy, suggesting that FAAH inhibitors could be beneficial for managing pain in diverse clinical contexts." (PMID 40075716, 2025).
Sepsis (2 papers, 2017 to 2021). Sepsis is defined as life-threatening organ dysfunction caused by a dysregulated host response to infection. "Fatty acid amide hydrolase mRNA levels in the whole blood of patients with sepsis is significantly reduced compared with healthy controls and remains low in sepsis mortality." (PMID 34087197, 2021).
sleep disorder (2 papers, 2021 to 2025). A change from the patient's baseline sleeping pattern, in the hours slept and/or an alteration/dysfunction in the stages of sleep. "In conclusion, we report associations between CNR1/FAAH polymorphisms and subjective/objective sleep quality in alcohol-associated sleep disturbances." (PMID 34566715, 2021).
stress-related disorder (2 papers, 2016 to 2025). Stress-related disorders are mental health disorders that are a result of an atypical response to both short and long-term anxiety due to physical, mental, or emotional stress. "Reversing FAAH hyperactivity can mitigate chronic stress effects, indicating that targeting FAAH may be a promising therapeutic strategy for stress-related disorders." (PMID 40787242, 2025). "However, other FAAH inhibitors have been shown to be safe in Phase 2 clinical studies and these may be pursued in the future for indications, for example, such stress-related disorders." (PMID 27790143, 2016).
substance abuse (2 papers, 2023 to 2025). The use of a drug for a reason other than which it was intended or in a manner or in quantities other than directed. "In candidate gene studies, SNPs in CNR1 (rs2023239) and FAAH (rs324420) have been associated with substance abuse and functional changes in cannabinoid regulation." (PMID 40442827, 2025). "In addition to its role in athletic performance, FAAH rs324420 is also involved in important mechanisms underlying human psychopathologies, including substance abuse and neural dysfunctions." (PMID 37895295, 2023).
abortion (1 paper, 2018). the ending of pregnancy by removing a fetus or embryo before it can survive outside the uterus. "In heifers, sheep, and women, the decrease in FAAH gene expression has been associated with abortions." (PMID 30089161, 2018).
absence seizures (1 paper, 2026). "In contrast to direct CB1 receptor agonists, which exacerbate absence seizures, FAAH inhibition preserves the spatial and temporal specificity of ECS, enabling circuit-restricted modulation of excitability." (PMID 41969140, 2026).
acute synovitis (1 paper, 2014). An acute inflammation of a synovial membrane. "The present study examined whether URB597, a potent and selective FAAH inhibitor, could alter inflammation and pain in a mouse model of acute synovitis." (PMID 25260980, 2014).
alcohol addiction (1 paper, 2011). "Besides, we wanted to evaluate the possible changes after chronic ethanol administration in two important elements of the endocannabinoid system that have been related to alcohol addiction: CB1 receptors and fatty acid amide hydrolase (FAAH) levels." (PMID 21886913, 2011).
alcoholic steatohepatitis (1 paper, 2021). "These compounds also have demonstrated potential in other conditions such as alcoholic steatohepatitis and diabetic nephropathy (peripherally restricted CB1 antagonists) and pain conditions (peripherally restricted CB1 agonists and FAAH inhibitors)." (PMID 34684760, 2021).
amyotrophic lateral sclerosis (1 paper, 2023). Amyotrophic lateral sclerosis (ALS) is a neurodegenerative disease characterized by progressive muscular paralysis reflecting degeneration of motor neurons in the primary motor cortex, corticospinal tracts, brainstem and spinal cord. "A transgenic model was created to investigate the role of FAAH in a common model of amyotrophic lateral sclerosis (ALS), by crossing the Cravatt strain FAAH-KO mice with SOD-Tg animals." (PMID 37958825, 2023).
anemia (1 paper, 2014). A reduction in the number of red blood cells, the amount of hemoglobin, and/or the volume of packed red blood cells. "Both high CNR2 and high FAAH levels correlated to anemia (p=0.0006 and p=0.038, respectively)." (PMID 25594062, 2014).
Anorexia (1 paper, 2022). Lack of desire to eat (loss of appetite). "This has also been elucidated to in humans wherein higher frequencies of the FAAH 385 C to A single nucleotide polymorphism (SNP) (hereafter rs324420) have been associated with anorexia and bulimia nervosa." (PMID 35980538, 2022).
Apathy (1 paper, 2025). Apathy is a quantitative reduction of interest, motivation and the initiation and persistence of goal-directed behavior, where often the accompanying emotions, thoughts, and social interactions are also diminished. "The relationship of greater fronto-limbic [11C]CURB λk3 to greater apathy along with the metabolic role of FAAH in the ECS, the latter which supports maintaining feelings of interest, initiative, and motivation, has important implications for the pathophysiology of apathy in MDD." (PMID 40550956, 2025).
asthma (1 paper, 2022). "Moreover, potential effects of AEA/FAAH signaling on other features of asthma are of interest." (PMID 36396957, 2022).
autism (1 paper, 2021). Persistent deficits in social interaction and communication and interaction as well as a markedly restricted repertoire of activity and interest as well as repetitive patterns of behavior. "Taken together, FAAH and MGL inhibitors attenuate autism-related symptoms in VPA-exposed male rats; however, they may exacerbate negative affective behaviours in VPA-exposed female rats." (PMID 34207178, 2021).
benign prostate hyperplasia (1 paper, 2010). "In benign prostate hyperplasia the basal cells expressed FAAH, whereas the luminal cells showed weak FAAH-IR, a finding entirely consistent with our data with the non-malignant tissue samples." (PMID 20808855, 2010).
bladder cancer (1 paper, 2020). "With the aim of better understanding the impact of the FAAH and NAAA expressions on bladder cancer development, we split patients into two groups—high and low expressors of these enzymes." (PMID 32260109, 2020). "To better understand the role of ECs and NAEs in bladder cancer, we analyzed gene expression data from TGCA database regarding the metabolic pathway of the ECS, comprising the synthetic enzymes (PLCB1-4, PTPN22, ABHD4, GDE1, DAGLA, DAGLB, and NAPE-PLD) and the hydrolytic ones (FAAH, NAAA, and MGLL)." (PMID 32260109, 2020).
bone cancer (1 paper, 2010). A primary or metastatic malignant neoplasm affecting the bone or articular cartilage. "Interestingly, a similar decrease of anandamide as a result of increased FAAH activity was recently found in the paw skin in bone cancer bearing mice." (PMID 20498712, 2010).
carcinosarcoma (1 paper, 2019). A malignant tumor composed of a mixture of carcinomatous and sarcomatous elements. "FAAH staining in carcinosarcoma showed very low intensity compared to that observed in the atrophic group, but involved both the glands and stroma." (PMID 31921630, 2019). "It was difficult to see the glandular structure in the carcinosarcoma, because the glands had been broken down and the epithelial cells dispersed throughout the tissue, but in those epithelial cells that were visible, FAAH staining was more cytoplasmic and localized to the apical region." (PMID 31921630, 2019). "When FAAH transcript levels were evaluated in the various grades of cancer, they were lower in grades 1, 2, and 3 type 1 tissues and higher in type 2 serous and carcinosarcoma EC when compared to the controls (even though these data were not statistically different)." (PMID 31921630, 2019).
colorectal adenocarcinoma (1 paper, 2023). The most common type of colorectal carcinoma. "The HT29 cell line showed high levels of FAAH expression, but the two other colorectal adenocarcinoma cell lines (DLD1 and HCT116) did not." (PMID 37921652, 2023).
dependence (1 paper, 2024). "Those with the FAAH C385A polymorphism, which reduces FAAH function, are at an increased risk for AUD due to higher alcohol intake and dependence severity." (PMID 39118031, 2024).
diabetic retinopathy (1 paper, 2016). "In one study, high glucose-mediated apoptosis in ARPE-19 RPE cells was reduced by the overexpression of FAAH, via CB1R blockade and via CB1R siRNA transfection, demonstrating a therapeutic potential for FAAH modulation in diabetic retinopathy." (PMID 26839718, 2016).
dyslipidaemia (1 paper, 2014). "However, in subcutaneous mature adipocytes from severely obese humans, FAAH and MGL enzyme activities are not altered in relation to BMI, waist circumference, adipose tissue distribution, blood pressure, fasting glucose or insulin, glycaemic control or dyslipidaemia." (PMID 24593280, 2014).